VCAM1 (vascular cell adhesion molecule 1)
Diseases named in the same sentence as VCAM1 in open-access papers (continued):
Sharing a sentence is not in itself a finding about the gene and the disease.
renal cell carcinoma (5 papers, 2018 to 2024). "In terms of renal cell carcinoma, VCAM-1 tumour cell expression is associated with better survival rate." (PMID 32933568, 2020). "These alterations may increase the risk for tumor formation; and in fact, the VCAM1 + proximal tubule is transcriptionally related to renal cell carcinoma." (PMID 38287344, 2024). "Interestingly, VCAM-1 can be exploited for immune evasion in cancer such as renal cell carcinoma, mainly by inhibiting CD8+ T cell infiltration." (PMID 38786066, 2024). "In general, these VCAM-1 are over expressed in cancer cells especially of that in renal cell carcinoma (RCC)." (PMID 30405190, 2018). "Axitinib, a TKI used to treat advanced renal cell carcinoma with profound HTN as a side effect in over 50% of patients, strongly suppressed LEENE and eNOS expression, while inducing VCAM1 expression, both in HUVECs and in mouse aortic rings cultured ex vivo." (PMID 37218991, 2023). "Examination of VCAM-1 overexpression in the Oncomine Cancer Profiling Database reveals that most tumors other than renal cell carcinoma do not upregulate VCAM-1." (PMID 38786066, 2024). "Interestingly, the lack of VCAM-1 expression has been postulated to be a potential biomarker for positive tumor vaccine response in some types of renal cell carcinoma." (PMID 38786066, 2024).
renal fibrosis (5 papers, 2013 to 2025). A final common manifestation of a wide variety of chronic kidney diseases characterized by glomerulosclerosis and tubulointerstitial fibrosis. "COL4A2, CXCL1, TIMP1, and VCAM1 have all been shown to be elevated in renal fibrosis, which is consistent with the findings of our experimental study." (PMID 37266443, 2023). "COL4A2, CXCL1, TIMP1, VCAM1, and VEGFA are promising diagnostic biomarkers of tissue and serum for renal fibrosis." (PMID 37266443, 2023). "In short, COL4A2, CXCL1, TIMP1, VCAM1, and VEGFA are promising diagnostic biomarkers of tissue and serum for renal fibrosis, which is helpful for the early diagnosis and treatment of patients with renal fibrosis." (PMID 37266443, 2023). "In this study, we observed that VCAM-1, ICAM-1, and MCP-1 expression were increased in HG-incubated NRK-52E cells and in experimental diabetic renal injury, which was associated with inflammatory cell infiltration and adhesion, and renal fibrosis." (PMID 24260158, 2013). "Five genes (COL4A2, CXCL1, TIMP1, VCAM1, and VEGFA) were subsequently identified as biomarkers for renal fibrosis through machine learning, and their expression levels were confirmed by validation cohort data sets and in vitro RT-qPCR experiment." (PMID 37266443, 2023). "Similarly, IL-6 drives renal fibrosis by activating STAT3 in fibroblasts and upregulating vascular cell adhesion molecule-1 (VCAM-1) expression in endothelial cells." (PMID 40534883, 2025).
rheumatic disease (5 papers, 2019 to 2022). "Briefly, all these findings provided evidence that kaempferol, an active ingredient of TWH, is sufficient to alleviate endothelial impairment and symptoms of rheumatic disease by down regulating ICAM-1and VCAM-1." (PMID 34259096, 2021).
sickle cell anemia (5 papers, 2013 to 2022). "Our results suggest that blood transfusion and adhesion factors, VCAM-1 and P-selectin, are potential therapeutic targets for addressing cerebrovascular pathology, such as vaso-occlusion, in sickle cell disease." (PMID 36570439, 2022). "Compared to a group of healthy controls, sickle cell disease patients had lower plasma zinc, increases in markers of oxidative stress, elevated VCAM-1, increased production of TNF-α and IL-1β, and decreased IFN-γ production at baseline." (PMID 34239993, 2021). "Abnormal adhesion of RBCs was first observed in sickle cell anemia involving vascular cell adhesion molecule (VCAM)-1, α4β1, Lu/BCAM, and intercellular adhesion molecule (ICAM)-4." (PMID 32727002, 2020).
small cell lung carcinoma (5 papers, 2013 to 2025). Small cell lung cancer (SCLC) is a highly aggressive malignant neoplasm, accounting for 10-15% of lung cancer cases, characterized byrapid growth, and early metastasis. "The anticancer effect of NARI is demonstrated by its ability to suppress small cell lung cancer cells growth through the miR-126/vascular cell adhesion molecule 1 (VCAM-1) signaling pathway." (PMID 40867875, 2025). "Regarding miR-181a, dysregulation of miR-181 family members has been reported for different types of cancer, such as small cell lung cancer with VCAM-1, an important factor in cell migration and invasion, being one of their targets." (PMID 32766179, 2020). "Chemotherapeutic agents such as cisplatin inhibit the migration and invasion of small cell lung cancer through decreasing the expression of VCAM-1." (PMID 23593320, 2013). "Vascular cell adhesion molecule-1 (VCAM-1) is expressed by endothelium in Hodgkin's disease and different cancers like small-cell lung carcinoma." (PMID 37280670, 2023).
Thrombocytopenia (5 papers, 2019 to 2025). A reduction in the number of circulating thrombocytes. "Low levels of sRAGE were associated with increased levels of IL-6, VCAM-1 and PAI-1 as well as with thrombocytopenia." (PMID 31635193, 2019). "Interestingly, a tree-structured model demonstrated that PvLDH, along with VCAM-1 and Syndecan-1, is a relevant predictor attribute (high information gain) in predicting thrombocytopenia severity in our cohort." (PMID 34585667, 2021). "In addition, other endothelial markers such as reduced soluble P‐selectin significantly correlated with prolonged thrombocytopenia and neutropenia, reduced VEGF‐A with prolonged neutropenia and anemia, and increased soluble VCAM‐1 (sVCAM‐1) with prolonged thrombocytopenia and anemia." (PMID 41368079, 2025).
vascular dementia (5 papers, 2011 to 2026). A degenerative vascular disorder affecting the brain. "In the chronic cerebral hypoperfusion model of vascular dementia, VCAM1 expression is increased in brain endothelia cells and correlates with BBB dysfunction." (PMID 41318967, 2026).
ZIKV infection (5 papers, 2020 to 2022). "ICAM1 and VCAM1 are involved in immune cell migration across the blood–brain barrier, where an increase in immune cells in the brain might contribute to the neuropathogenesis associated with intrauterine ZIKV infection." (PMID 32380717, 2020). "We observed that ZIKV infection led to selective upregulation of CAMs (VCAM1, ICAM1, and SELE) whereas PECAM was downregulated upon ZIKV AF infection (≤2-fold, P value ≤ 0.05 compared to CT), confirming the data obtained previously with the array." (PMID 32753493, 2020). "Interestingly VCAM1 and ICAM1, encoding two cell adhesion molecules (CAMs) involved in leukocyte docking to the BBB, were also upregulated upon ZIKV infection." (PMID 32753493, 2020). "Significant increase in the gene expression of various laminin alpha-chains as well as fibril forming collagen chains was seen in ZIKV-infected TEC, as well as higher levels of VCAM1 and ICAM-1 expression in TEC after ZIKV infection." (PMID 31992777, 2020).
acute pancreatitis (4 papers, 2009 to 2023). An acute inflammatory process that leads to necrosis of the pancreatic parenchyma. "Blockage of VCAM-1 resulted in decreased recruitment and adherence of leukocytes into the lungs, thus inhibiting lung injury in severe acute pancreatitis." (PMID 34830018, 2021). "VCAM-1 expression is known to be positively correlated with the extent of organ damage in the animal model of acute pancreatitis." (PMID 34830018, 2021). "ICAM-1, VCAM-1, E-selectin and P-selectin have been found to play an important pro-inflammatory role in various models of acute pancreatitis." (PMID 20040116, 2009).
airway hyperresponsiveness (4 papers, 2012 to 2022). "In the ovalbumin mice model, anti‐VCAM1 reduced airway hyperresponsiveness and eosinophilic inflammation." (PMID 35754128, 2022).
anemia (4 papers, 2021 to 2025). A reduction in the number of red blood cells, the amount of hemoglobin, and/or the volume of packed red blood cells. "The increased circulatory VCAM-1 and ICAM-1 levels in CA mice further underline these findings implicating the role of anemia in inflammation and associated changes in the endothelium." (PMID 37234375, 2023). "During the recovery process from anemia early EBI niches are enriched with phenotypically more monocyte-like cells expressing high CD11b and Ly6C but low F4/80, CD169and Vcam-1 levels." (PMID 34367164, 2021). "Strikingly, we also observed increased plasma ICAM-1 and VCAM-1 levels in chronic coronary syndrome (CCS) patients with anemia compared to non-anemic patients." (PMID 37234375, 2023).
Arrhythmia (4 papers, 2021 to 2025). Any cardiac rhythm other than the normal sinus rhythm. "MG could attenuate VCAM-1, ICAM-1, MCP-1, and MMP9, inhibit the proliferation of smooth muscle cells and fibroblasts, and obtain arrhythmia from I/R injury to show cardiovascular protection." (PMID 33815113, 2021).
astrocytoma (4 papers, 2004 to 2024). "A restricted set of tumor-associated genes was identified for each grade that included genes not previously associated with astrocytomas (e.g. VCAM1, SMOC1, and thymidylate synthetase), with a high percentage of cell surface genes." (PMID 15265232, 2004). "Moreover, cannabinoid receptor-independent inhibition of VCAM-1 and ICAM-1 expression is not new and has previously been described in astrocytoma cells using the synthetic cannabinoid R(+)WIN 55.212-2, where inhibition of transactivation of NF-κB was shown to be the underlying mechanism." (PMID 39768198, 2024).
bladder cancer (4 papers, 1996 to 2023). "Moreover, naringin inhibited cell migration and invasion of chondrosarcoma cells via vascular cell adhesion molecule 1 (VCAM-1) down-regulation by increasing miR-126, while in bladder cancer cells it downregulated the Akt and MMP-2 pathways." (PMID 27827912, 2016).
chronic hepatitis (4 papers, 2012 to 2024). An active inflammatory process affecting the liver for more than six months. "Consistently elevated expression of VCAM-1 in chronic liver diseases imply its association with conditions such as chronic hepatitis or CIR." (PMID 39286634, 2024). "However, despite this, the clinical significance of increased serum VCAM-1 in HCC patients remains largely unexplored, even though the majority of HCC cases are associated with underlying chronic hepatitis or CIR." (PMID 39286634, 2024). "We used HSECs treated with IFN-γ and TNF-α in flow-based adhesion assays to model inflamed HSEC, which express ICAM-1, VCAM-1, and CXCR3 ligands in chronic hepatitis." (PMID 22796894, 2012).
chronic obstructive pulmonary disease (4 papers, 2016 to 2023). A chronic and progressive lung disorder characterized by the loss of elasticity of the bronchial tree and the air sacs, destruction of the air sacs wall, thickening of the bronchial wall, and mucous accumulation in the bronchial tree. "During pulmonary pathogenesis in chronic obstructive pulmonary disease (COPD), human NRP-1+ ILC3 located in proximity to blood vessels and lung ectopic lymphoid tissues, where they induced VCAM-1 and ICAM-1 expression on mesenchymal stromal cells, and efficiently responded to VEGF-A." (PMID 37234993, 2023).
dermatomyositis (4 papers, 2013 to 2025). Dermatomyositis (DM) is a type of idiopathic inflammatory myopathy characterized by evocative skin lesions and symmetrical proximal muscle weakness. "• Dermatomyositis (DM) patients had higher circulating ICAM-1 and VCAM-1 levels compared to healthy controls." (PMID 40055821, 2025). "MiR-126 is proposed to play a specific role in the early but not in the late stage of juvenile dermatomyositis by promoting the expression of the vascular cell adhesion molecule 1 (VCAM-1), a protein normally expressed in developing but not in mature healthy muscle fibers." (PMID 24137130, 2013). "However, the positive clinical effects of high-dose IVIG on muscle function in patients with refractory inflammatory active myositis in the form of polymyositis or dermatomyositis are not accompanied by any effects on ICAM-1 and VCAM-1." (PMID 26714881, 2015).
diabetic neuropathy (4 papers, 2021 to 2025). A chronic, pathological complication associated with diabetes mellitus, where nerve damages are incurred due to diabetic microvascular injury involving small blood vessels that supply these nerves, resulting in peripheral and/or autonomic nerve dysfunction. "Among the different adhesion molecules, VCAM-1 was the only significantly associated molecule for diabetic neuropathy (OR=0.999, 95%CI=0.997-1.0, p=0.028)." (PMID 36843591, 2023). "This suggests that VCAM-1 levels may not always directly correlate with clinical improvements in diabetic neuropathy." (PMID 39727989, 2024).
epilepsy (4 papers, 2016 to 2024). A brain disorder characterized by episodes of abnormally increased neuronal discharge resulting in transient episodes of sensory or motor neurological dysfunction, or psychic dysfunction. "The most pronounced epilepsy-associated differences were decreased levels of eotaxin, IL-1β, C-reactive protein, and vascular cell adhesion molecule (VCAM)-1 and increased IL-12 p70 levels." (PMID 27737716, 2016). "Vascular mediators CRP, ICAM-1, and VCAM-1 all showed epilepsy-related differences." (PMID 27737716, 2016). "Systemic leukocytes infiltrate the brain from the blood stream through VCAM-1 (Vascular Adhesion Molecule 1) and ICAM-1 (Intercellular Adhesion Molecule 1) adhesion molecules, trans-endothelial diapedesis, and blood–brain barrier disruption promoting epilepsy- associated neuroinflammation." (PMID 38166692, 2024). "Thus, age- and epilepsy-related differences were confirmed for the hippocampal VCAM-1 levels." (PMID 27737716, 2016). "We found that FK506 not only had direct neuroprotective effects but also inhibited the expression of inflammatory factors VCAM-1, ICAM-1, PKCδ, and TNF-α after seizures, thereby indirectly inhibiting the development of epilepsy." (PMID 31572289, 2019). "The results showed that the VCAM-1 and ICAM-1 mRNA levels in the epilepsy group were highest at 24 h after SE, which were significantly higher than those in the control group." (PMID 31572289, 2019). "Besides, FK506 also significantly reduced the levels of factors involved in inflammatory response such as vascular cell adhesion molecule-1 (VCAM-1), intercellular adhesion molecule-1 (ICAM-1), tumor necrosis factor-α (TNF-α), and Protein Kinase C δ (PKCδ) that rise after epilepsy." (PMID 31572289, 2019). "While nonepileptic cases comprised a very small, nonage-matched sample, this might have implications for epilepsy-related changes in hippocampal VCAM-1." (PMID 27737716, 2016). "Vascular cell adhesion molecule (VCAM)-1 levels did not appear different across brain regions overall but showed multiple effects among the nonepileptic cases (epilepsy effect p < 0.0001, brain region effect p < 0.0001, epilepsy × brain region interaction p < 0.0001)." (PMID 27737716, 2016).
experimental autoimmune encephalomyelitis (4 papers, 2011 to 2023). An autoimmune demyelinating disease of the central nervous system that is produced experimentally in animals by the injection of homogenized brain or spinal cord in Freund's adjuvant. "Vascular cell adhesion molecule-1 (VCAM-1) has been shown to be important in the development of experimental autoimmune encephalomyelitis (EAE) and MS, mediating both leukocyte movements across the BBB and their retention within the parenchyma." (PMID 24592383, 2014). "However, somewhat paradoxically, in earlier studies, IFN-β was shown in murine models of experimental autoimmune encephalomyelitis (EAE) to decrease the abundance of adhesion molecules on brain capillaries such as ICAM-1 and VCAM-1." (PMID 37239045, 2023). "Ultrastructural studies in an experimental autoimmune encephalomyelitis model revealed polar localization of ICAM-1, VCAM-1, and MAdCAM-1 on the apical surface of choroid plexus epithelial cells and their complete absence on the fenestrated endothelial cells within the choroid plexus parenchyma." (PMID 21592385, 2011).
gastric tumor (4 papers, 2016 to 2024). "A proposed mechanism of H. pylori-mediated gastric cancer progression is through VCAM1 upregulation in gastric CAFs, which in turn potentiates the invasiveness of gastric tumor cells via binding to their αVβ5/1 integrins." (PMID 39120310, 2024). "Meanwhile, mRNA levels of NF-kB downstream metastasis-related genes including Vimentin, MMP-2, MMP-9, VEGF, ICAM-1 and VCAM-1 were significantly enhanced in the primary gastric tumors." (PMID 30728051, 2019). "Similarly, the infection of human stomach fibroblasts with Helicobacter pylori, a pathogen commonly found in gastric tumor tissues, promotes the expression of VCAM1 via activation of JAK/STAT1 signaling." (PMID 39120310, 2024). "In gastric tumours, VCAM-1-positive tumours are more invasive, later disease and more metastatic compared to VCAM-1 negative tumours." (PMID 31217905, 2019).
glomerulonephritis (4 papers, 2011 to 2023). A renal disorder characterized by damage in the glomeruli. "For patients in whom concurrent renal biopsies had also been performed, urine VCAM-1 exhibited the strongest association with the renal pathology activity index and glomerulonephritis class IV, although it correlated negatively with the chronicity index." (PMID 22788914, 2012). "Interestingly, urinary VCAM-1 was also elevated in anti-neutrophil cytoplasmic antibodies-associated glomerulonephritis, focal segmental glomerulosclerosis and membranous nephropathy but not in minimal-change disease." (PMID 22788914, 2012). "Both ICAM-1 and VCAM-1 cortical mRNA expression showed a significant increase in LPS-induced glomerulonephritis compared to control mice." (PMID 37475889, 2023). "Both glomerular ICAM-1 and VCAM-1 protein expression were increased in mice with LPS-induced glomerulonephritis compared to control mice." (PMID 37475889, 2023). "Both cortical ICAM-1 and VCAM-1 mRNA expression were increased in LPS-induced glomerulonephritis in our study while the four treatments could only reduce the ICAM-1 mRNA expression and not the VCAM-1 mRNA expression." (PMID 37475889, 2023). "In bacteria-induced glomerulonephritis, lipopolysaccharide (LPS, a key component of the outer membranes of Gram-negative bacteria) stimulated VCAM-1 induction in the murine glomerular mesangium." (PMID 23153039, 2012).
glomerulosclerosis (4 papers, 2021 to 2024). A hardening of the kidney glomerulus caused by scarring of the blood vessels. "P. gingivalis LPS may induce diabetic renal inflammation, such as glomerulosclerosis and tubulitis with infiltration of Mac-1/podoplanin-positive macrophages, via glomerular overexpression of vascular cell adhesion molecule-1 (VCAM-1) and E-selectin." (PMID 34211440, 2021). "RAGE vaccination in db/db mice attenuated urinary albumin excretion, podocyte injury, and glomerular sclerosis, as well as reduced ICAM–1 and VCAM–1 production." (PMID 37007029, 2023).
Hepatic steatosis (4 papers, 2010 to 2023). Steatosis is a term used to denote lipid accumulation within hepatocytes. "The treatment with APs or atorvastatin induced a remarkable reduction in the atherosclerotic lesions and hepatic steatosis and decreased the levels of low-density lipoprotein, triglyceride, CCL-2 and VCAM-1 levels in the plasma." (PMID 26305254, 2015). "Together, VCAM-1 in HSCs does not contribute to liver steatosis, inflammation or fibrosis development in the course of NAFLD/NASH, as assessed in two different experimental models." (PMID 36902241, 2023).